VIM (vimentin)
Diseases named in the same sentence as VIM in open-access papers (continued):
Sharing a sentence is not in itself a finding about the gene and the disease.
Sepsis (13 papers, 2019 to 2026). Sepsis is defined as life-threatening organ dysfunction caused by a dysregulated host response to infection. "Our previous studies, along with extensive research linking vimentin to these critical pathways, support the feasibility of vimentin modulation to simultaneously target multiple pathogenic components of sepsis." (PMID 41157235, 2025). "An observational study reported that high levels of serum vimentin in pediatric patients with severe sepsis predicts a high-risk hospital mortality in these patients." (PMID 39207603, 2024). "However, it remains undefined if the expression of this abnormal vimentin is directly linked to the dysregulated host immune response and sustained systemic inflammation induced by sepsis." (PMID 39207603, 2024). "Recently, it has been associated with sepsis, and therefore, this could explain high concentrations of vimentin found in saliva in a pyometra group." (PMID 32596263, 2020). "Thus, HPX has been linked in a co-expression protein network with vimentin in patients diagnosed with sepsis and septic shock." (PMID 31554244, 2019). "Furthermore, vimentin contributes to sepsis-associated coagulopathy." (PMID 41157235, 2025). "An aberrant plasma vimentin was identified to associate with fibrinogen in the swine model of sepsis-induced coagulopathy. pre- and 70 h post-infected plasma samples were fractionated by size-exclusion chromatography and the fibrinogen eluate analyzed for the presence of associated vimentin." (PMID 39207603, 2024). "In sepsis, persistent or excessive insults drive vimentin-mediated overactivation, uncoupling these programs and propagating systems-level instability that culminates in organ dysfunction." (PMID 41900975, 2026). "Vimentin-knockout mice exhibit reduced lung injury and improved survival following challenge with LPS, a microbial mediator of sepsis and systemic inflammation." (PMID 41157235, 2025). "Collectively, these findings highlight vimentin’s involvement across key immune cell types and its potential role in driving the immunosuppressive state of late-stage sepsis." (PMID 41157235, 2025). "As a key regulator of infection and host response, vimentin serves as a central node for multiple cellular processes relevant to sepsis, including microbial infection and clearance, inflammation and immunosuppression, and coagulation and metabolism." (PMID 41157235, 2025). "These preclinical findings indicate that the vimentin-targeting agent ALD-R491 represents a promising therapeutic candidate for sepsis and merits further clinical investigation." (PMID 41157235, 2025). "Using cecal ligation and puncture (CLP) in mice, we demonstrated that targeting vimentin significantly reduced sepsis-related mortality." (PMID 41157235, 2025). "This study has identified 5 key genes – CTSD, GADD45A, MAPK14, MMP9, and VIM – that are significantly upregulated in sepsis patients compared to healthy controls." (PMID 40184094, 2025). "The expression levels of CTSD (P < .001), GADD45A (P < .001), MAPK14 (P < .001), MMP9 (P < .001), and VIM (P < .001) were significantly higher in patients with sepsis than in normal healthy controls." (PMID 40184094, 2025). "This study evaluated the efficacy of ALD-R491, a novel small-molecule vimentin modulator, in a murine model of polymicrobial sepsis induced by cecal ligation and puncture (CLP)." (PMID 41157235, 2025). "Five hub genes including CTSD, GADD45A, MAPK14, MMP9, and VIM were upregulated in patients with sepsis compared with normal controls in the GSE28750 (peripheral blood samples) and GSE64457 (neutrophil samples) datasets." (PMID 40184094, 2025). "In sepsis patients, circulating vimentin levels are significantly elevated and correlate with hospital mortality, suggesting that vimentin is a promising therapeutic target for sepsis." (PMID 41157235, 2025). "Another clinical study supports the use of serum vimentin level as a biomarker for diagnosing and predicting the prognosis of sepsis." (PMID 39207603, 2024).
Sepsis (continued). "Future studies will be necessary to explore whether phosphorylated Ser 71 or other post-translational modifications (PTMs) in vimentin are a major determinant in the ability of aberrant vimentin to engage fibrinogen, cause changes in the fibrin formation potential and the clot structure in sepsis." (PMID 39207603, 2024). "To test if the large animal model replicates a human manifestation of the dysregulated host immune response leading to coagulopathy due to sepsis, we investigated the level of plasma vimentin and its ability to modulate fibrin polymerization potential." (PMID 39207603, 2024). "Previously, we also described the elevated levels of extracellular (plasma) vimentin in the circulation of patients with sepsis." (PMID 39207603, 2024). "Consistently, knockdown of vimentin expression significantly increases lymphocyte apoptosis in the context of sepsis, whereas vimentin overexpression results in the opposite outcome." (PMID 38915055, 2024). "The RT-qPCR data showed that the mRNA levels of α-SMA and Vimentin in sepsis-induced ARDS group were lower, but E-cadherin was higher than those of control group and pneumonia-induced ARDS group (P < 0.01)." (PMID 36478088, 2023). "The disruption of Vimentin intermediate filaments in lymphocytes results in increased cell death and the release of soluble vimentin into blood circulation, which is related to the worse outcome of sepsis." (PMID 35573702, 2022). "One of the studies is focused on the clinical value of vimentin and the mechanism of vimentin-mediated immune cell apoptosis during sepsis development." (PMID 35573702, 2022). "These regulatory responses of vimentin in the LPS injury model demonstrate the role of Vimentin intermediate filaments in immunosuppression during sepsis." (PMID 35573702, 2022). "In the current study, screening of proteomics results revealed that serum vimentin concentration increased at different stages of sepsis." (PMID 30952998, 2019). "The serum concentrations of vimentin in sepsis or septic shock were significantly higher than that in the control group (204.34 ± 52.53 ng/ml or 283.06 ± 102.52 ng/ml vs. 117.36 ± 38.93 ng/ml, respectively, p < 0.001)." (PMID 30952998, 2019). "We have further performed proteomics analysis of blood samples collected from patients with sepsis or septic shock, and we found that serum vimentin levels were significantly increased in these patients." (PMID 30952998, 2019). "In summary, vimentin is a unique target engaged in multiple aspects of sepsis pathogenesis." (PMID 41157235, 2025). "We assess its impact on hyperinflammation, organ injury, disease severity, and survival, aiming to determine whether vimentin modulation offers a viable therapeutic approach for sepsis." (PMID 41157235, 2025). "To assess the therapeutic potential of the small-molecule vimentin modulator ALD-R491 in sepsis, we employed a cecal ligation and puncture (CLP)-induced sepsis model in mice, using mortality rate as the primary endpoint and disease severity as the secondary endpoint." (PMID 41157235, 2025). "These therapeutic effects, together with previously characterized mechanisms of action, provide compelling preclinical proof-of-concept that vimentin targeting represents a promising strategy for developing effective sepsis therapeutics and warrants further clinical investigation." (PMID 41157235, 2025). "Although prior research has established roles for vimentin in regulating diverse cellular processes implicated in sepsis pathology, the present study was not designed to characterize these mechanisms in septic mice." (PMID 41157235, 2025). "Thus, our data suggested that elevated levels of an aberrant vimentin contribute to coagulopathy by directly interacting with fibrinogen and enhancing fibrin formation in patients with sepsis." (PMID 39207603, 2024).
Sepsis (continued). "Thus, our swine model of sepsis-induced coagulopathy, reproduced increased extracellular circulating vimentin and subsequent potentiation of fibrin formation, often observed in septic patient." (PMID 39207603, 2024). "Finally, this study supports the notion that elevated levels of a modified or phosphorylated extracellular vimentin during sepsis impacts fibrin formation potential and significantly modify the structure of fibrin clots." (PMID 39207603, 2024). "Therefore, this study aimed to determine if our swine model of sepsis-induced coagulopathy replicates the increment of a distinct plasma vimentin and to assess the capacity of anti-vimentin on reducing fibrin formation ex vivo in the swine plasma." (PMID 39207603, 2024). "We previously published on the ability of recombinant vimentin and, more specifically, the rod domain of vimentin (rhRod), to bind P-selectin and block leukocyte adhesion and inflammation in experimental models of sepsis." (PMID 38473724, 2024). "Together, these reports suggest that extracellular vimentin serves as a potential biomarker in sepsis and may be considered for early identification and timely therapeutic interventions for patients with severe sepsis." (PMID 39207603, 2024). "Western blotting results demonstrated that the Snail1, α-SMA, and Vimentin protein expressions in AECIIs of patients with sepsis-induced ARDS were upregulated markedly, while the expression of E-cadherin was lower than those of control group and pneumonia-induced ARDS group (P < 0.01)." (PMID 36478088, 2023). "This trial will determine whether the vimentin can be a new target for sepsis diagnosis and treatment (NCT03253146)." (PMID 35573702, 2022). "Patients with sepsis and septic shock have increased levels of vimentin in serum." (PMID 35573702, 2022). "The authors also showed that, the expression of vimentin by lymphocytes was significantly higher in sepsis patients compared to healthy controls; furthermore, among sepsis patients, the vimentin level on lymphocytes was significantly higher in deceased patients." (PMID 34966382, 2021). "Vimentin may prevent lymphocyte apoptosis and be anti-inflammatory and, thus, may be a useful new target in sepsis." (PMID 31554244, 2019). "In this context, vimentin expression increased in lymphocytes isolated from sepsis patients." (PMID 30952998, 2019). "The current study demonstrated that serum vimentin concentration was significantly increased in patients with sepsis, which may result from the increased expression and degradation of vimentin in lymphocytes isolated from septic patients." (PMID 30952998, 2019). "The vimentin expression in lymphocytes showed the same tendency, i.e., the septic shock had the highest, the control group had the lowest, and the sepsis group had moderate level of expression (81.65 ± 29.06 and 37.7 ± 14.25 vs. 65.42 ± 14.65, respectively, p < 0.001)." (PMID 30952998, 2019). "In this study, we found that serum vimentin concentrations increased during sepsis, suggesting that vimentin might be cleaved and released from the cytosol into the circulation." (PMID 30952998, 2019). "Modulating vimentin with ALD-R491 offers a host-directed antimicrobial strategy, which may be particularly useful for controlling infections caused by unknown or multidrug-resistant pathogens in sepsis." (PMID 41157235, 2025). "Thus, one can argue that targeting fibrin clot structure with anti-vimentin antibody could be a potential therapy for patients with sepsis-induced coagulopathy in the future." (PMID 39207603, 2024). "Findings from our in vitro experiments with Jurkat cells indicated that vimentin may protect lymphocytes from apoptosis and that suppression of vimentin in lymphocytes may augment the inflammatory response in sepsis through upregulation of inflammatory cytokine release." (PMID 30952998, 2019).
Sepsis (continued). "We have identified vimentin as a potential target protein in patients with different stages of sepsis through iTRAQ protein quantification and further verified that vimentin may be used to differentiate between sepsis and septic shock or even predict the prognosis of sepsis." (PMID 30952998, 2019). "Therefore, soluble vimentin in the circulation could be a biomarker for the diagnosis and prognosis of sepsis." (PMID 30952998, 2019). "Patients with sepsis had a significantly higher expression of CTSD, GADD45A, MAPK14, MMP9, and VIM than normal health controls." (PMID 40184094, 2025). "ALD-R491, the first oral small molecule specifically targeting vimentin, significantly reduced hyperinflammation, mitigated organ damage, and improved survival in the CLP-induced sepsis model." (PMID 41157235, 2025). "Here, we tested the status of plasma vimentin and its impact on fibrin clots using our recently described swine model of methicillin-resistant Staphylococcus aureus (MRSA) sepsis-induced coagulopathy." (PMID 39207603, 2024). "Compared to control group and pneumonia-induced ARDS group, the epithelial marker E-cadherin protein expression decreased, while the expressions of Snail1, Vimentin, and α-SMA proteins increased significantly in AECIIs of patients with sepsis-induced ARDS." (PMID 36478088, 2023). "By modulating vimentin, ALD-R491 could offer the potential to inhibit both hyperinflammation and immunosuppression in sepsis." (PMID 41157235, 2025). "The dual role of vimentin in both hyperinflammation and immunosuppression could present a unique opportunity for ALD-R491 to address the conflicting pathologies of sepsis, an area where other therapies have fallen short." (PMID 41157235, 2025). "The orally administered vimentin modulator ALD-R491 dose-dependently reduced inflammation, protected multiple organs from injury, alleviated disease severity, and improved survival in CLP-induced sepsis." (PMID 41157235, 2025). "In addition, APS may inhibit LPS-induced increase in α-SMA and Vimentin expression, but increase the expression of E-cadherin, suggesting that APS may play a role in inhibiting EMT in sepsis-induced AKI." (PMID 33575163, 2021). "It was demonstrated that serum vimentin (VIM) levels were significantly increased in patients with sepsis and septic shock compared to controls and that VIM expression was significantly increased in lymphocytes isolated from septic shock and sepsis patients compared to controls." (PMID 30952998, 2019). "However, evidence of vimentin involvement in sepsis has not previously been reported." (PMID 30952998, 2019).
soft tissue sarcoma (13 papers, 2011 to 2022). A malignant neoplasm arising from muscle tissue, adipose tissue, blood vessels, fibrous tissue, or other supportive tissues excluding the bones. "On the other hand, it has been shown that AKT activation induces increased vimentin phosphorylation, leading to the protection of vimentin against caspase-induced proteolysis and increased cell survival and migration in soft tissue sarcoma cells." (PMID 34203746, 2021). "Activation of Akt in soft-tissue sarcoma cells promotes the interaction of the head region of VIM and the tail region of Akt, resulting in the phosphorylation of VIM at Ser-39, further enhancing cell motility and invasion." (PMID 32047143, 2020). "Recent work has shown that Withaferin A targets vimentin in soft tissue sarcomas resulting in vimentin cleavage and apoptosis, increasing the promise for vimentin as a target in cancers of mesenchymal origin." (PMID 28910304, 2017). "Histopathological evaluation of the mass revealed features consistent with a soft tissue sarcoma and positive staining was observed for vimentin and S-100." (PMID 26101678, 2015). "Moreover, it has been reported that AKT activation increases soft-tissue sarcomas cell motility and invasiveness at least partially through its interaction with vimentin." (PMID 34203746, 2021). "In line with the cell migration-promoting role of vimentin through its interactions with signaling proteins, hyperphosphorylation of Akt target site on vimentin, S39, has been shown to enhance migration and invasion of soft tissue sarcoma, and metastasis in a xenograft model." (PMID 31126068, 2019). "Cells were positive for vimentin, but negative for other proteins, which supports the soft tissue sarcoma diagnosis." (PMID 22615950, 2012). "We aimed to investigate the prognostic impact of TGF-β1, NF-κB p105, PKC-ζ, Par-6α, E-cadherin and vimentin in non-gastrointestinal stromal tumor soft tissue sarcomas (non-GIST STSs)." (PMID 21390241, 2011). "Likewise, the in vivo growth of soft tissue sarcoma cells implanted in female SCID (severely combined immunodeficient) mice was inhibited by i.p. administration of withaferin-A, which reduced cell proliferation and induced apoptosis via degradation of vimentin." (PMID 26959007, 2016).
Arthritis (12 papers, 2008 to 2026). Inflammation of a joint. "Like previous Pre-RA studies we could identify particular ACPA reactivities targeting, for example, citrullinated vimentin and enolase with association to arthritis progression, but in comparison presence of at least one ACPA reactivity was in our study a stronger predictive factor." (PMID 38457608, 2024). "DNA damage was observed in T cells, vimentin positive FLS and other synovial cells in RA-risk individuals, pre-RA and arthritis patients." (PMID 41571322, 2026). "And shikonin reduced the number of vimentin+cells in collagen induced arthritis mice inflamed joints." (PMID 34600581, 2021). "However, PAD 2 and PAD 4 are the only isotypes acting upon proteins such as fibrin and vimentin in the synovial tissue of patients with arthritis, and can generate an immune response by converting into antigenic elements." (PMID 26946202, 2016). "Moreover, in animals treated with QFGJS, it was found not only to suppress proteins expressions related to the pathogenesis of arthritis but even activate expression of some proteins like Vim vimentin, C-reactive protein, and Np purine nucleoside phosphorylase." (PMID 23781264, 2013).
Autoimmunity (12 papers, 2006 to 2024). The occurrence of an immune reaction against the organism's own cells or tissues. "T cells highly expressing K-Ras would induce autoimmunity, which was mediated by citrullinated vimentin-derived peptide, a pathogenic autoantigen in RA." (PMID 34393779, 2021). "As vimentin is a known antigenic target in B-cell-mediated autoimmunity, we investigated in situ humoral anti-vimentin responses in pulmonary sarcoidosis and their relationship with HLA-DRB1*03." (PMID 30038611, 2018). "The intermediate filament protein vimentin is involved in essential cellular processes, including cell division and stress responses, as well as in the pathophysiology of cancer, pathogen infection, and autoimmunity." (PMID 34203497, 2021). "Furthermore, recent data point to the role of vimentin in RA synovial fibroblasts as mediators of autoimmunity, since autophagy in these cells induces vimentin citrullination and interaction with MHC-II." (PMID 32630064, 2020). "The ubiquity of citrullination of vimentin in the lungs and other tissues suggests that the relationship between smoking and autoimmunity in RA may be more complex than previously thought." (PMID 25600626, 2015). "Although the mechanism of induction of autoantibodies against vimentin still remains obscure, proteolysis of the intact, native protein may play a role in development of autoimmunity." (PMID 18769604, 2006). "Interestingly, both strains showed similar levels of antibodies at a young age though antibodies to self-antigens, Vimentin and ANP, were significantly higher in aged *0402 mice, P < 0.05 even though *0402 mice are not susceptible to autoimmunity." (PMID 31836763, 2019). "Finally, the finding of vimentin-specific autoreactive CD8+ T-cells in heart recipients have shown that transplantation cellular response, as for the humoral response, may spread from being directed to allo-antigens to autoimmunity." (PMID 25374567, 2014).